STAT3 (signal transducer and activator of transcription 3)
Diseases named in the same sentence as STAT3 in open-access papers (continued):
Sharing a sentence is not in itself a finding about the gene and the disease.
glioblastoma (continued). "miR-21 inhibitor loaded dendrimers enhance chemosensitivity of glioblastoma cells to paclitaxel through EGFR/STAT3 signaling." (PMID 33007959, 2020). "All these results demonstrate that cardamonin has the ability to be a new anticancer agent for glioblastoma by virtue of its ability to act as a STAT3 inhibitor." (PMID 32545187, 2020). "STAT3 and its inhibition has been explored rather extensively with regard to its oncogenic role and the identification of novel therapeutic targets in glioblastoma." (PMID 32967361, 2020). "Based on the TCGA datasets and primary cell lines prepared from the tissue samples of glioblastoma patients, the levels of active STAT3 and stem cell markers were positively correlated with the survival rate." (PMID 32183406, 2020). "Glioblastoma-derived IL6 is required for up-regulation of myeloid PD-L1 in glioblastoma through a STAT3-dependent mechanism." (PMID 32403421, 2020). "The activities included the suppression of migration, invasion, viability, stem cell properties, and tumor growth, induction of apoptotic cell death, and extension of survival rate by targeting STAT3 in glioblastoma cells, GSCs and glioblastoma xenografts." (PMID 32183406, 2020). "STAT3 Ser727 phosphorylation is also associated with radioresistance and has been reported to correlate with shortened overall survival and progression-free survival of GBM (glioblastoma) patients." (PMID 32872659, 2020). "In the present study, we observed that the level of active STAT3 was relatively higher in primary cell lines prepared from the tissue samples of glioblastoma patients, and the level was concurrent with the survival rate of the patients." (PMID 32183406, 2020). "Constitutively activated STAT3 plays an essential role in the initiation, progression, maintenance, malignancy, and drug resistance of cancer, including glioblastoma, suggesting that STAT3 is a potential therapeutic target for cancer therapy." (PMID 32183406, 2020). "As reported 47, p-STAT3 expression was significantly increased in glioblastoma tissues compared to that in normal brain tissues (paired Student's t-test)." (PMID 31534499, 2019). "Signal transducer and activator of transcription 3 (STAT3) is aberrantly activated in glioblastoma and has been identified as a relevant therapeutic target in this disease and many other human cancers." (PMID 31247937, 2019). "For example, it has been shown that FOXM1 upregulates the expression and activity of STAT3 in a β-catenin-dependent manner in glioblastoma cells." (PMID 31390744, 2019). "In particular, we identified that stellettin B inhibits the Akt/Girdin and Stat3 signaling pathways, which leads to the downregulation of invasion, migration, and angiogenesis in glioblastoma cells." (PMID 30769863, 2019). "Overall, glioblastoma tumor development and progression is highly dependent on STAT3 activation for cell proliferation, mesenchymal transition and invasion with prognostic value." (PMID 31698775, 2019). "STAT3 and ANGPTL4 (encode Angiopoietin-like 4) are directly correlated in glioblastoma patients and increased expression of these genes results in poor survival." (PMID 31534498, 2019). "Our results indicate that Napabucasin suppresses the expression of STAT3, and thus impairs the proliferation, migration, and invasion of glioblastoma cells." (PMID 31277685, 2019). "Although there a wide a range of in vitro studies showing the importance of Stat3 in glioblastoma, there are only a few clinically oriented studies that correlate Stat3 expression with patient survival." (PMID 31690341, 2019).
glioblastoma (continued). "Using a published set of validated STAT3 targets from chromatin immunoprecipitation (ChIP)-sequencing (ChIP-seq) assays, performed with glioblastoma cells, we generated a list of 308 genes that were also present in our WP + B/RX2 + B datasets." (PMID 31455240, 2019). "In the previous experiments, inhibition of STAT3 protein is found highly effective to suppress Glioblastoma tumor cells." (PMID 31263189, 2019). "In glioblastoma, CSCs produce cytokines via activation of the STAT3 pathway to recruit and polarize macrophages to become M2-like cells, in turn, M2- like cells serve as a CSC niche to enhance CSC growth." (PMID 31579438, 2019). "Altogether, hypoxia and Stat3 are involved in promoting glioblastoma stem-like cells, thus increasing tumour resistance and invasiveness." (PMID 31690341, 2019). "Signal transducer and activator of transcription 3 (Stat3) is a key signaling protein driving major hallmarks of cancer and represents a promising target for the development of targeted glioblastoma therapies." (PMID 30857197, 2019). "For instance, endogenous STAT3 activation or expression of a constitutively active form of STAT3 inhibits glioblastoma cell proliferation and invasiveness." (PMID 31297057, 2019). "IGFBP2 was previously reported to augment the nuclear accumulation of EGFR and to potentiate STAT3 transactivation via nuclear EGFR signaling pathway in glioblastoma." (PMID 31801484, 2019). "IL-6 was found to be necessary for myeloid PD-L1 induction through a signal transducer and activator of STAT3-dependent mechanism in glioblastoma." (PMID 31192256, 2019). "It was observed that inhibition of STAT3 protein strongly affected the development of all grades of Glioblastoma tumor cells." (PMID 31263189, 2019). "Through its expression, it promotes the activation of neoangiogenesis in glioblastoma, highlighting the role of Stat3 in cellular adaptation in extreme conditions." (PMID 31690341, 2019). "Further, stellettin B downregulates Akt/Mammalian Target of Rapamycin (Akt/mTOR) and Signal transducer and activator of transcription 3 (Stat3) signaling pathways, which are essential for invasion and angiogenesis in glioblastoma." (PMID 30769863, 2019). "We thus propose a model of signaling pathways in the STAT3/CEBPD/PDGFA axis mediating inflammatory factor-induced stemness in glioblastoma." (PMID 31300060, 2019). "Our results show that Stat3 expression can be evaluated by immunohistochemistry and has an important prognostic role in glioblastoma." (PMID 31690341, 2019). "Knockdown of MiR-21 in glioblastoma mouse xenografts showed marked reduction in tumor growth as well as reduction of hTERT and STAT3 expression." (PMID 30189661, 2018). "HES5 has been shown to increase activation of STAT3 and STAT3 promotes glioblastoma stem cell renewal, and acts synergistically with Nanog to maintain pluripotency of embryonic stem cells." (PMID 30555629, 2018). "This study demonstrates that postoperative resveratrol administration efficiently improves the prognosis of rat advanced orthotopic glioblastoma via inhibition of growth, induction of apoptosis and inactivation of STAT3 signalling." (PMID 30176837, 2018). "Another study found that MiR-21 plays a major role in carcinogenesis of glioblastoma mediated through STAT3, a transcription factor largely involved in the differentiation of TH17 helper T cells." (PMID 30189661, 2018). "Other studies have further supported the essential role of the JAK2/STAT3 signaling for EGFRvIII-driven glioblastoma cell migration and invasion by promoting focal adhesion and stabilizing the EGFRvIII/JAK2/STAT3 axis." (PMID 30279357, 2018). "We conclude that STAT3 is essential for forming glioblastoma and plays a substantial role in the cancer stem-like properties of radioresistant GBM." (PMID 30551687, 2018).
glioblastoma (continued). "The phosphorylated EZH2 directly binds to and methylates STAT3, leading to enhanced STAT3 activity by increasing phosphorylation of STAT3 at Y705 and thereby promotes the tumorigenicity of glioblastoma and glioblastoma stem-like cells (GSCs)." (PMID 29556394, 2018). "EZH2 has also been shown to methylate non-histone substrates; EZH2-mediated methylation of STAT3 leads to STAT3 activation and increased glioblastoma tumorigenicity." (PMID 30022044, 2018). "The phosphorylated EZH2 also can directly bind to and methylate STAT3, leading to enhanced STAT3 activity by increased tyrosine phosphorylation of STAT3 and thereby promote the tumorigenicity of glioblastoma stem-like cells (GSCs)." (PMID 29556394, 2018). "Consistent with this, human glioblastoma cell lines exposed to IL-22 show increases in both STAT3 and Akt phosphorylation." (PMID 30542269, 2018). "The main finding of this study is that YM155 decreased radiation-induced invasion and reversed epithelial–mesenchymal transition by targeting STAT3 in glioblastoma." (PMID 29571296, 2018). "They use the Gint4.T aptamer as a targeting agent conjugated to a STAT3 siRNA to target STAT3 inhibition to glioblastoma cells." (PMID 30340426, 2018). "A reduction of STAT3 by CBD has previously been shown in glioblastoma cells where it was for example related to the inhibition of self-renewal." (PMID 30150937, 2018). "STAT3 has furthermore been shown to play a central role in maintenance of a stem cell phenotype in glioblastoma." (PMID 30555629, 2018). "STAT3 signaling is critical for glioblastoma cells including RG2 cells and is the major molecular target of resveratrol." (PMID 30176837, 2018). "In the present study, we demonstrated that the survival of CD133+ stem-like cells in glioblastoma depends on STAT3 activity." (PMID 29284440, 2017). "We first examined Jmjd3 expression in response to STAT3 inhibition in two glioblastoma stem cell lines, GS6-22 and GS7-2, which we have previously characterized." (PMID 28384648, 2017). "Further study showed that CUR exerted its antitumor activity involved in reactivation of receptor activator of NF-κB and inactivation of STAT3 in glioblastoma cells." (PMID 28881600, 2017). "The elevated ROS production by NOX4 plays a vital role for STAT3 activation and angiogenesis in hypoxic glioblastoma cells." (PMID 28594389, 2017). "STAT3, then, regulates neurosphere formation and proliferation in normal embryonic neural stem cells as well as in glioblastoma stem cells." (PMID 28384648, 2017). "There was less information available for these mutual feedback regulatory axis; one study showed that regulation of EZH2 was involved in positive feedback loop with β-catenin/transcription factor 4 (TCF4) and Stat3 signaling in glioblastoma cells." (PMID 28360411, 2017). "It has been reported that silencing HDAC7 in glioblastoma (GMB) cell U87 enhanced STAT3 phosphorylation by upregulating JAK1 expression." (PMID 29126425, 2017). "Overexpression of Jmjd3 slows glioblastoma stem cell growth and neurosphere formation, whereas knockdown of Jmjd3 rescues the STAT3 inhibitor-induced neurosphere formation defect." (PMID 28384648, 2017). "Hypoxia also leads to a 30–50% increase in angiogenesis and cell migration by signal transducer and activator of transcription 3 (STAT3) phosphorylation in glioblastoma cells." (PMID 28594389, 2017). "We and others have previously shown that the transcription factor STAT3 is essential for glioblastoma stem cell proliferation and multipotency." (PMID 28384648, 2017). "In conclusion, we have presented the first evidence linking SH3GL2 to malignant behaviours of human glioblastoma through STAT3/MMP2 pathway." (PMID 28470949, 2017). "In summary, we have found that curcumin targets glioblastoma stem cells though the induction of ROS, potentially through downregulation of STAT3 activity." (PMID 28160777, 2017).
glioblastoma (continued). "Another study proved that EZH2 was able to directly bind to and methylate STAT3, thereby promoting the tumorigenicity of glioblastoma and prostate CSCs." (PMID 28415635, 2017). "The activation of JAK2/STAT3 pathway, which is overactivated in glioblastomas, promotes cell migration and invasion in several types of cancer." (PMID 28168193, 2017). "STAT3 is abnormally activated in glioblastoma and has been considered as a valuable therapeutic target in this disease and numerous other human cancers." (PMID 28470949, 2017). "The growth factor and cytokine regulated transcription factor STAT3 is required for the self-renewal of several stem cell types including tumor stem cells from glioblastoma." (PMID 28384648, 2017). "We have shown that STAT3 maintains normal neural and glioblastoma stem cells in a proliferative, self-renewing state via the repression of the histone demethylase Jmjd3." (PMID 28384648, 2017). "We and others have previously demonstrated that Nanog is the direct downstream effector of Stat3 in the regulation of tumorigenicity and self-renewal of liver CSCs and glioblastoma stem cells." (PMID 28186991, 2017). "There is an IL-6 based positive feedback loop in glioblastoma where extracellular IL-6 results in intracellular STAT3 phosphorylation (activation) that in turn upregulates glioblastoma cells’ IL-6 synthesis." (PMID 28977822, 2017). "The transient receptor potential cation channel, subfamily M, member 7 (TRPM7) also leads to increased cancer stem cell proliferation in glioblastoma multiforme (GBM) through activation of the JAK2/STAT3 and/or Notch signaling pathways." (PMID 28219421, 2017). "Convergence of STAT3’s position with different oncogenic signaling pathways is one of the main reasons for its prevalence in glioblastoma." (PMID 28346397, 2017). "This is consistent with studies in glioblastoma showing that inhibition of IL-6 or its receptor, IL-6Rα, diminishes STAT3 activation and, in turn, the number of glioblastoma stem cells." (PMID 26880966, 2016). "Mir-520e is involved in the NIK/p-ERK1/2/NF-κB signaling in hepatocarcinogenesis having as direct target NIK gene, while mir-519a acts in STAT3 pathways and is correlated with poor outcome in glioblastoma." (PMID 27600084, 2016). "STAT3 plays a key regulatory role in the expression of hTERT in several cancer cell lines including gastric, breast and glioblastoma, and hTERT in turn contributes to the survival of these STAT3-dependent tumors." (PMID 27548225, 2016). "It has been shown that EZH2 methylates STAT3 in glioblastoma stem-like cells which is required for the activation of STAT3-dependent activation of stem cell-associated transcriptional factors and efficient tumorsphere formation." (PMID 27764181, 2016). "Staining showed that STAT3 and p-STAT3 were undetectable in normal brain tissues, expressed at a high level in untreated glioblastoma tissues and remarkably decreased in resveratrol-treated tumors, particularly in the regions with extensive cell death." (PMID 27716625, 2016). "STAT3 signaling is critical for glioblastoma cells and is the major molecular target of resveratrol." (PMID 27716625, 2016). "Constitutive activation of STAT3 by phosphorylation has been reported in 70% of human cancers, including glioblastoma." (PMID 27145367, 2016). "In conclusion, LP-delivered resveratrol efficiently inhibited orthotopic rat glioblastoma growth by inactivating STAT3 signaling and enhancing autophagy and apoptosis." (PMID 27716625, 2016). "Studies show that STAT3 phosphorylation at tyrosine 705 is abnormal aggregation in malignant glioma cells, particularly in glioblastoma." (PMID 26788112, 2015). "In fact, it has been shown that reduction of microRNA-21 in U87 and LN229 glioblastoma cells repressed STAT3 expression and STAT3 phosphorylation." (PMID 26225961, 2015).
glioblastoma (continued). "Further study showed that curcumin exerted its antitumor activity involved in reactivation of RANK (receptor activator of nuclear factor κB) and inactivation of STAT3 (signal transducer and activator of transcription 3) in glioblastoma cells." (PMID 26046466, 2015). "More recently, it has been shown that in a subset of glioblastomas the EGFR-driven activation of STAT3 requires: a." (PMID 25885672, 2015). "The role of STAT3 in regulating chemoresistance has recently been emphasized in cancer cells such as glioblastoma multiforme (GBM) and neuroblastoma." (PMID 25638155, 2015). "Recently, Cucurbitacin I was shown to inhibit JAK2/STAT3 and induce autophagy and apoptosis in glioblastoma cells in vitro and in flank xenograft studies." (PMID 25237832, 2014). "This is in contrast to SOCS3, another endogenous inhibitor of STAT3, which is a direct transcriptional target of STAT3 and highly expressed in primary tumors from glioblastoma multiforme patients." (PMID 25268165, 2014). "More recently, other authors report that STAT3 and NF-κB signaling regulates the Notch pathway in glioblastoma cancer stem cells." (PMID 25380967, 2014). "The importance of the IL-6/STAT3 axis has been linked to supporting CSC populations in a variety of cancers, including hepatocellular, breast, head and neck cancers and glioblastoma." (PMID 24722453, 2014). "Expression of active Jak2 and/or STAT3 has been observed in a number of immortalized glioblastoma cell lines and primary cells." (PMID 25162558, 2014). "To identify proteins that interact with INPP5F, we performed co-immunoprecipitation (Co-IP) experiments using anti-V5 with INPP5F overexpressing cells, and found that INPP5F co-precipitated with STAT3 in glioblastoma cell lysates." (PMID 25476455, 2014). "We found that the T98G glioblastoma cell line expresses a high level of active Jak2 (ie, pJak2), and that treatment with G6 reduced Jak2/STAT3 phosphorylation in a dose-dependent manner." (PMID 25162558, 2014). "The expression of PIAS3 has been shown to be reduced in glioblastoma, and this finding correlates with an elevated level of STAT3 activation and increased cell proliferation." (PMID 24995504, 2014). "Radiosensitization after STAT3 modulation has also been shown using RNAi-based approaches in U87 and U251 glioblastoma cells in vitro and in vivo." (PMID 25268165, 2014). "The expansion of CSCs can be measured by the formation of tumorspheres and STAT3 activation has been shown to be critical for neurosphere formation in glioblastoma and tumorsphere formation in human colon cancer cells." (PMID 23555719, 2013). "We silenced STAT3 using siRNA in two human glioblastoma multiforme cell lines (U251 and U87), and investigated the effect on cell adhesion and invasion." (PMID 24386409, 2013). "The link between the activation of STAT3 and glioblastoma biology has become increasingly convincing." (PMID 23998913, 2013). "STAT3 activation in conjunction with C/EBP-β correlates with mesenchymal transformation of glioblastomas and is inversely related to outcome." (PMID 23998913, 2013). "Recent results from glioblastoma studies also showed that the IL-6/STAT3 pathway is required for proliferation, survival and tumor growth of glioblastoma stem cells." (PMID 24376586, 2013). "In this study, we silenced STAT3 using Small interfering RNAs in two human glioblastoma multiforme (GBM) cell lines (U251 and U87), and investigated the effect on GBM cell adhesion and invasion." (PMID 24386409, 2013). "This is consistent with previous study which also showed STAT3 binds to the promoter region of hTERT in human glioblastoma." (PMID 24386318, 2013). "Stat3 has been postulated as a potential target against TICs for various tumor types, including glioblastoma multiforme." (PMID 22879872, 2012). "Nuclear EGFRvIII has also been found to cooperate with STAT3 to activate COX-2 gene expression in glioblastoma cells, resulting in glioma tumorigenesis." (PMID 22520625, 2012).